OXTR (oxytocin receptor)
Diseases named in the same sentence as OXTR in open-access papers (continued):
Sharing a sentence is not in itself a finding about the gene and the disease.
depression (continued). "Moreover, administration of OXTR antagonist or viral knockdown of OXTR expression in nucleus accumbens produced depression-like behavior in male pair-bonded prairie voles after separation from their partner and even in the presence of their partner." (PMID 38798348, 2024). "Interestingly, when post-mortem studies with the brains of patients suffering from major depressive disorder, bipolar disorder, and schizophrenia were tested, the levels of OXTR mRNA were increased in the dorsolateral prefrontal cortex." (PMID 36835321, 2023). "Methylation analyses of 9 promoter/regulatory regions of genes known to be implicated in depression/PTSD (ADCYAP1, BDNF, CRHR1, DRD2, IGF2, LSD1/KDM1A, NR3C1, OXTR, SLC6A4) were performed on DNA from blood samples by the MassARRAY EpiTYPER platform, with MassCleave settings." (PMID 36001138, 2023). "On the other hand, earlier studies on OXTR methylation strongly suggested that functions of the oxytocin system, including OXTR-mediated signal transduction, may be involved in the attenuation of the fear response, which can protect against depression." (PMID 36835321, 2023). "An interesting hypothesis was proposed that the mechanism by which defects in OXTR influence the development of depression is based on the dysfunctional social processes occurring in the absence of fully active OXTR." (PMID 36835321, 2023). "Preclinical findings suggest that long-term isolation down-regulates OXTR mRNA transcription and contributes to the development of depression in isolated mice – which might be attenuated through intracentral amygdala injection of OXT." (PMID 35672748, 2022). "Recent research suggests that the polymorphisms of the oxytocin receptor (OXTR) affect the neurocardiac response to the HPA function, suggesting that OXTR may have regulatory effects on the pathomechanisms of depression." (PMID 36583185, 2022). "OXTR expression was found significantly higher also in peripheral blood lymphocytes of first episode schizophrenia patients, and in the dorsolateral prefrontal cortex of individuals with major depression and bipolar disorder." (PMID 35361281, 2022). "For rs53576, maternal rejection, OXTR gene polymorphism and ethnicity did not significantly predict depression." (PMID 35564961, 2022). "Another candidate gene for depression is the oxytocin receptor (OXTR) gene." (PMID 35564961, 2022). "We hypothesize that methylation levels (%) of the oxytocin receptor promoter region correlate with the severity of depression symptoms and/or with the severity of childhood trauma within this present sample of affective disorder patients." (PMID 35672748, 2022). "For rs53576, paternal rejection was a significant predictor of depression, R2diff = 0.184, p < 0.001, while OXTR gene polymorphism and ethnicity did not significantly predict depression." (PMID 35564961, 2022). "For rs2254298, maternal rejection, OXTR gene polymorphism and ethnicity did not significantly predict depression." (PMID 35564961, 2022). "Hence, the present study aims to investigate the influence of OXTR rs53576 and rs2254298 genotypes on depression in the context of parental rejection in childhood by examining gene–environment interactions." (PMID 35564961, 2022). "For rs2254298, paternal rejection was a significant predictor of depression, R2diff = 0.183, p < 0.001, while OXTR gene polymorphism and ethnicity did not significantly predict depression." (PMID 35564961, 2022). "In female subjects, adverse events in adulthood (financial pressure, high crime neighborhood) may induce methylation pattern changes in OXTR and may increase vulnerability to depression." (PMID 34073101, 2021). "Furthermore, it is noteworthy that the interaction effect of OXTR rs53576 genotype × maternal postpartum depression on externalising problems in the present study was evident even when the history of maternal affective disorder was adjusted for." (PMID 31118457, 2019).
depression (continued). "To replicate and extend these findings, we examined whether three literature-based OXTR SNPs (rs2254298, rs53576, rs2268498) interact with childhood maltreatment in the development of clinically diagnosed depression and anxiety disorders." (PMID 28353027, 2017). "That is, GWA studies have not implicated a role for the OXTR, and only one candidate gene study so far has shown associations of depression with OXTR SNPs." (PMID 28353027, 2017). "Genome wide association studies (GWAS), including a mega-analysis, have not yielded any direct associations between OXTR gene polymorphisms and depressive disorders." (PMID 28353027, 2017). "The overall model was statistically significant and again young adult depression was significantly predicted by the hypothesized three-way interaction of Sex × OXTR × Parental divorce status." (PMID 26441708, 2015). "However we identified a significant three-way interaction between OXTR rs53576 genotype, OXTR methylation, and depression in pregnancy in both unadjusted (p = 0.0192) and adjusted (p = 0.0081) models." (PMID 26257770, 2015). "In a similar approach, the objective of the present study was to evaluate, in a sample of older women, the association of anxiety disorders and/or depression with a specific DNA methylation according to SNVs in four candidate genes: SLC6A4, BDNF, OXTR, and APOE." (PMID 26175754, 2015). "The overall model was statistically significant at p < 0.10 and young adult depression was significantly predicted by the hypothesized three-way interaction of Sex × OXTR × Parental divorce status." (PMID 26441708, 2015). "Moderated mediation analyses conducted using bootstrapping procedures and confidence intervals based on 5000 resamples showed that, as expected, the OXTR genotype moderated the mediating role of distrust in the relation between childhood maltreatment and depression scores." (PMID 23898235, 2013). "In contrast, the OXTR SNP rs237885 did not associate with maternal behavior, but it did associate with pre-natal (but not post-natal) depression score." (PMID 23637833, 2013). "In the current investigation, there was no direct associated found between the OXTR genotypes and depression scores." (PMID 23898235, 2013). "Also, the OXTR rs2254298 GG-genotype seemed to be protective with respect to depressive and anxious symptoms in adolescent girls whose mothers had suffered from depression." (PMID 23284802, 2012). "On the other hand, the occurrence of depression in pregnancy did not associate with DNA methylation changes at the OXTR locus in the cells of the placenta; however, cord plasma antidepressant levels were associated with an increased level of the methylation at the OXTR promotor region." (PMID 36835321, 2023). "Current research on the influence of oxytocin, OXTR, and OXTR DNA methylation on mental health and depression particularly led to mixed results with unanswered questions: Still, it is unknown whether peripheral oxytocin levels in clinically depressed patients differ from those in healthy persons." (PMID 34822109, 2022). "In this comparison set, the controls were chosen for the cases that were depressed prenatally in order to assess whether there were OXTR genetic/DNA methylation relationships among the women who continued to be depressed compared with those whose depression had resolved by 8 weeks postpartum." (PMID 26257770, 2015). "However, there has been evidence suggesting an OXTR gene by environment interaction on various human traits (e.g., emotional dysregulation and attachment style) or psychiatric diseases (e.g., depression)." (PMID 26599592, 2015). "Our primary hypothesis was that increased methylation of OXTR enhances risk of PPD in women contingent on OXTR genotype (rs53576_GG vs. A allele) and that this might differ according to the presence or absence of depression during pregnancy." (PMID 26257770, 2015).
depression (continued). "This study confirmed that the OXTR rs53576 genotype which was also found in other psychiatric disorders, such as ASD, BPD, ADHD, and Schizophrenia, was in connection with PTSD/depression comorbidity." (PMID 37153633, 2023). "There is evidence suggesting that both Major Depression Disorder (MDD) and Bipolar Disorder (BPD) patients show increased expression of OXTR mRNA in the dorsolateral prefrontal cortex compared to patients with schizophrenia and controls." (PMID 35672748, 2022). "Pathological blunting of the OXTR protomers in 5-HT2AR and especially in 5-HT2CR heteroreceptor complexes can contribute to the development of depression and other types of psychiatric diseases involving disturbances in social behaviors." (PMID 33672070, 2021). "It seems likely that pathological blunting of the OXTR protomers in 5-HT2AR and especially in 5-HT2CR heteroreceptor complexes can contribute to the development of depression and other types of psychiatric diseases involving disturbances in social behaviors." (PMID 33672070, 2021). "The potential moderating role that a polymorphisms of oxytocin (OXTR), rs53576 (GG), may have in relation to a significant adolescent stressful life event (parental divorce) in terms of depression in adolescence and young adulthood has not been investigated and is the focus of this study." (PMID 26441708, 2015). "A recent study reported an interaction between rs53576 and OXTR DNA methylation in women who did not have depression prenatally but developed postnatal depression." (PMID 41470006, 2025). "Remitting patients differed from non-remitting patients regarding urinary oxytocin and OXTR DNA methylation, indicating oxytocin-related subgroups of depression." (PMID 34822109, 2022). "The rs139832701 SNP in OXTR interacted with ELS to predict increased stress and depression scores." (PMID 31428006, 2019). "The objectives of the present study were to verify whether older women with anxiety disorder/depression differ from control subjects according to DNA methylation and genotypes at SNVs in BDNF, OXTR, SLC6A4, and APOE." (PMID 26175754, 2015). "There was evidence of an interaction between rs53576 and methylation in the OXTR gene amongst women who did not have depression prenatally but developed PPD (p interaction = 0.026, adjusted for covariates, n = 257)." (PMID 26257770, 2015). "For example, people with the GA or GG genotype of OXTR rs53576 were prone to seek social support from others, especially when they faced negative emotion and showed decreased reactivity to negative events and depression." (PMID 39767874, 2024). "Further detail showed that women who do not display depression in pregnancy, but who harbor the rs53576_GG genotype and display high methylation in OXTR are nearly three times as likely to develop PPD, in comparison to women of lower methylation levels or carrying the rs53576 A allele." (PMID 26257770, 2015). "Indeed, the development of a depressive-like behavior in mice treated with a selective oxytocin receptor antagonist does not necessarily mean specificity of OXTR dysfunction to depression but rather may suggest a general behavioral disturbance." (PMID 36835321, 2023). "The role of peripheral oxytocin and markers of the oxytocin receptor gene (OXTR) — the gene that guides the oxytocin receptor — on social affiliation, trust, and mood has been studied extensively in humans, suggesting that it may also be involved in clinical depression." (PMID 34822109, 2022). "The hypothesis goes beyond the serotonin hypothesis of depression and moves into molecular integration performed in diverse 5-HT1A and other 5-HTR heterocomplexes where, e.g., fibroblast growth factor receptor 1 (FGFR1) and oxytocin receptor protomers participate." (PMID 33672070, 2021).
autism spectrum disorder (43 papers, 2009 to 2025). A spectrum of developmental disorders that includes autism, and Asperger syndrome. "The results of studies with almost 4000 autistic patients were included in this analysis, which demonstrated significant associations between autism spectrum disorder and the following OXTR SNPs: rs7632287, rs237887, rs2268491, rs2254298." (PMID 36835321, 2023). "Various single nucleotide polymorphisms (SNPs) in the oxytocin receptor (OXTR) gene have been associated with behavioral traits, autism spectrum disorder (ASD) and other diseases." (PMID 34980886, 2022). "Increases in OXTR DNAm were associated with callous-unemotional traits in youth, social cognitive deficits in Autistic Spectrum Disorder (ASD), rigid thinking in anorexia nervosa, affect regulation problems, and problems with facial and emotional recognition." (PMID 29843655, 2018). "In fact, several studies report associations between SNPs in the oxytocin receptor (OXTR) gene, and autism spectrum disorder (ASD)." (PMID 29530929, 2018). "One recent meta-analysis study found significant association between autism spectrum disorder and the rs7632287, rs237887, rs2268491, and rs2254298 SNPs of OXTR." (PMID 26599592, 2015). "This study shows that, the OXTR intronic SNP rs2268494 detected as being under balancing selection is associated with reactions to betrayal as well as the autism spectrum disorder (ASD)." (PMID 25968600, 2015). "The human oxytocin receptor (hOXTR) is implicated in the etiology of autism spectrum disorders (ASDs) and is a potential target for therapeutic intervention." (PMID 23815867, 2013). "Regarding a broader spectrum of disorders of social cognition, preliminary evidence points to an involvement of OXTR rs2254298, whose A-allele was considered a risk for autism spectrum disorder in Chinese Han families and in a Japanese case-control study." (PMID 23284802, 2012). "DNA methylation of OXTR decreases expression of the gene and high levels of methylation have been associated with autism spectrum disorders (ASD)." (PMID 23087634, 2012). "We have reported association OXTR htSNPs previously in an association study of autism spectrum disorder (ASD)." (PMID 19461999, 2009). "The oxytocin receptor (OTR) regulates critical physiological functions and has been implicated in a range of diseases, including psychiatric and neurodevelopmental disorders such as autism spectrum disorder." (PMID 41001975, 2025). "According to the results of our analysis, other positively selected variants of the OXTR gene are associated with aggressive behavior and depressive states, alcohol abuse and associated aggressive behavior, severe schizophrenia, and autism spectrum disorders." (PMID 38002996, 2023). "The aim of the presented study was to analyze the clinical picture of social cognition deficits in boys with autism spectrum disorders and to relate its elements with the frequency of alleles of selected polymorphisms within the oxytocin receptor (OXTR) and vasopressin receptor 1A (AVPR1A) genes." (PMID 37190654, 2023). "One such focused and extensive work led to the proposal that social impairment and repetitive behaviors observed in patients with autism spectrum disorder might be associated with polymorphisms in the OXTR 3′UTR." (PMID 36835321, 2023). "In the light of the contradictory conclusions drawn on the basis of results from different studies on the OXTR gene polymorphisms and autism spectrum disorder, a meta-analysis was performed to assess if there were any connections between the SNPs in this gene and the development of the disease." (PMID 36835321, 2023). "Perhaps surprisingly, the results did not support the hypothesis about the role of common polymorphisms in the OXTR gene in the development of autism spectrum disorder, at least in the Caucasian population." (PMID 36835321, 2023). "Intronic SNPs on OXTR are further associated with autistic spectrum disorder (ASD)." (PMID 25968600, 2015).
autism spectrum disorder (continued). "The SNP rs13316193 C allele of the OXTR gene has been associated with empathy, whereas the T allele has been linked to decreased expression of oxytocin receptors in the brain, depressive mood, and greater risk for autism spectrum disorder." (PMID 26599592, 2015). "An association between the OXTR rs53576 and autism spectrum disorder has also been reported." (PMID 25538588, 2014). "In addition, many studies have demonstrated that single-nucleotide polymorphisms (SNPs) of the OXTR gene are associated with autism spectrum disorders (ASDs), social anxiety disorders, and schizophrenia." (PMID 23815867, 2013). "The oxytocin receptor gene has single‐nucleotide polymorphisms (SNPs) and SNPs of the oxytocin receptor gene have been shown to be associated with difference in pair bonding, empathy and stress responsiveness, generous behaviour, prosocial temperament, face recognition, and autism spectrum disorder." (PMID 34713517, 2021). "Further support for the connection of genetic changes in OXTR with autism spectrum disorder came from a more robust analysis in which 18 SNPs in this gene were tested." (PMID 36835321, 2023). "Another complex investigation demonstrated that the cumulative genetic variation in OXTR impacts the reward system connectivity in patients with autism spectrum disorder, as well as in neurotypical controls." (PMID 36835321, 2023). "The oxytocin receptor (OXTR) knockout mouse is a model of autism spectrum disorder, characterized by abnormalities in social and olfactory behaviors and learning." (PMID 36817409, 2022). "And lastly, the oxytocin receptor (Oxtr) because of its pivotal role in social function and autism spectrum disorders." (PMID 33834423, 2021). "The neuropeptide oxytocin (OT) and its receptor (OXTR) have been predicted to be involved in the regulation of social functioning in autism spectrum disorders (ASD)." (PMID 28484366, 2017). "Furthermore, recent analyses on the use of artificial neural networks indicated that changes in methylation levels of the OXTR gene were specific to females with autism spectrum disorder." (PMID 36835321, 2023). "In summary, there are many results suggesting that disturbed levels and activities of OXTR may considerably contribute to the development of autism spectrum disorder." (PMID 36835321, 2023). "For instance, ethnicity moderates the relation between OXTR genotypes and engagement in emotion suppression; and allelic associations with autism spectrum disorder generalize across Chinese and Japanese samples but not white." (PMID 35146961, 2022). "Variations in oxytocin receptor (OXTR) expression may play a role in the social deficits seen in autism spectrum disorder." (PMID 35858098, 2022). "It has been hypothesized that the amygdala, an OXTR-dense area of the brain, plays an important role in the processing of emotional and social information and in the development of autism spectrum disorders." (PMID 30873056, 2019). "However, another study performed with Japanese patients did not support the contribution of OXTR polymorphisms to autism spectrum disorder susceptibility." (PMID 36835321, 2023). "In addition to their roles in enhancing social behaviors, the AVPR1a and oxytocin receptor (OXTR) genes have been shown by us and others to contribute to autism spectrum disorders (ASD), a behavioral disorder characterized by deficits in social communication and bonding." (PMID 19461999, 2009). "Given the data observed within the OXTR deletion family, we hypothesized that DNA methylation of residues found within the critical region of OXTR regulation may extend beyond this family and represent a more general epigenetic contribution to autism spectrum disorders." (PMID 19845972, 2009). "Additionally, many have speculated that OXTR is involved with autism spectrum disorders." (PMID 21980460, 2011).
autism spectrum disorder (continued). "In a very recent robust synthesis of published evidence of candidate genes for autism spectrum disorder, the authors failed to determine the credibility of the evidence for OXTR." (PMID 36835321, 2023).